CRYZ (crystallin zeta)
Description:
Multifunctional crystallin endowed with unrelated mRNA stabilization and enzymatic oxidoreductase activities. Binds (AU)-rich elements (ARE) in the 3'-UTR of target mRNA to enhance their stability. Upon metabolic acidosis, stabilizes the mRNA encoding SLC12A1 a cotransporter involved in transepithelial NH4(+) reabsorption in the medullary thick ascending limb in kidney (By similarity). In response to acidosis, also participates to the adaptive increase in renal ammoniagenesis by stabilizing the mRNAs of enzymes involved in glutamine catabolism (By similarity). By the same mechanism, it also regulates the expression of the antiapoptotic protein BCL2. Beside its mRNA stabilization activity, also catalyzes the reduction of orthoquinones such as 1,2-naphthoquinone or 9,10-phenanthrenequinone in the presence of NADPH in vitro and could be involved in the detoxification of xenobiotics and protection against oxidative stress.
Tractability: Small molecule: a structure with a bound ligand is known; it has a high-quality binding pocket. PROTAC: ubiquitination databases record sites on it; its protein half-life has been measured; a small molecule that binds it is known.
Target class: Enzyme; Oxidoreductase
Gene: Protein-coding gene on chromosome 1 (74,701,488 to 74,733,104, reverse strand). Ensembl gene ENSG00000116791.
Subcellular location: Cytoplasm, cytosol
Subcellular location (Human Protein Atlas): Cytosol
Gene Ontology:
Molecular function: identical protein binding; mRNA 3'-UTR binding; NADH binding; NADPH binding; protein binding; quinone reductase (NADPH) activity; oxidoreductase activity; zinc ion binding
Biological process: protein homotetramerization; xenobiotic catabolic process; visual perception; mRNA stabilization
Cellular component: cytosol; extracellular exosome; mitochondrion
Genetic constraint (gnomAD): Loss-of-function variants: 37 observed, 31.45 expected, observed/expected ratio (o/e) 1.18, 90% interval 0.9 to 1.55. The upper end of that interval is the gene's LOEUF score, 1.55, which puts it in group 6 of 6, group 1 being the genes least tolerant of losing a copy. Missense variants: 312 observed, 334 expected, observed/expected ratio (o/e) 0.93, 90% interval 0.85 to 1.03. Synonymous variants: 115 observed, 117.15 expected, observed/expected ratio (o/e) 0.98, 90% interval 0.84 to 1.15.
Homologues: Orthologues: chimpanzee CRYZ (99% identical), rabbit CRYZ (87% identical), dog CRYZ (87% identical), pig CRYZ (84% identical), guinea pig CRYZ (83% identical), mouse Cryz (81% identical), rat Cryz (81% identical), zebrafish cryz (68% identical), tropical clawed frog cryz (67% identical), Caenorhabditis elegans F39B2.3 (41% identical). Paralogues in human: VAT1 (31% identical), VAT1L (30% identical), TP53I3 (29% identical), ADH6 (27% identical), RTN4IP1 (27% identical), ADH1A (25% identical), ADH1B (24% identical), ADH1C (24% identical), ADH5 (24% identical), SORD (23% identical), MECR (22% identical), ADH4 (22% identical), and 5 more.
Diseases named in the same sentence as CRYZ in open-access papers:
CRYZ is named in the same sentence as 26 diseases in open-access papers, as found by Europe PMC text mining. Sharing a sentence is not in itself a finding about the gene and the disease. The quoted sentences say what the papers report.
Insulin resistance (3 papers, 2018 to 2025). Increased resistance towards insulin, that is, diminished effectiveness of insulin in reducing blood glucose levels. "CRYZ encodes for zeta-crystallin, nicotinamide-adenine dinucleotide phosphate-dependent quinone reductase, and TYW3 for tRNA-wybutosine synthesis protein 3 homolog, two metabolic proteins associated with insulin resistance, a clinical feature with a high prevalence to PD." (PMID 35883433, 2022).
colorectal cancer (2 papers, 2022). A primary or metastatic malignant neoplasm that affects the colon or rectum. "Both TEX45 and zeta crystallin (CryZ) are expressed in several human cancer types including colorectal cancer." (PMID 35884586, 2022).
hepatocellular carcinoma (1 paper, 2018). A malignant tumor that arises from hepatocytes. "SLC1A4 was found to be associated with human hepatocellular carcinoma, and CRYZ was proven to be involved in B-cell lymphoma 2 (BCL-2) overexpression in T-cell acute lymphocytic leukemia." (PMID 29344347, 2018).
leukaemia (1 paper, 2024). "Among the Bcl–2 AUBPs we identified Zeta-Crystallin (CryZ), demonstrating its role in increasing Bcl-2 mRNA stability in human leukaemia cell lines." (PMID 39021835, 2024).
non-small cell lung carcinoma (1 paper, 2011). A group of at least three distinct histological types of lung cancer, including non-small cell squamous cell carcinoma, adenocarcinoma, and large cell carcinoma.
ovarian carcinoma (1 paper, 2024). A malignant neoplasm originating from the surface ovarian epithelium. "Cytotoxicity assays were conducted in A2780S and A2780R ovarian cancer cells to evaluate if CryZ binding activity inhibition and CryZ silencing were able to reverse cisplatin resistance." (PMID 39021835, 2024). "Here, we show that ASA inhibits the binding of CryZ to the mRNAs of Bcl-2 and Bcl-xl, two important anti apoptotic genes and that it is able to revert the drug resistance in ovarian cancer cells." (PMID 39021835, 2024). "Here, we investigated the role of CryZ as a novel therapeutic target in A2780 ovarian carcinoma cells by modulating the protein activity with acetylsalicylic acid (ASA) to restore chemosensitivity." (PMID 39021835, 2024). "ASA-treatment or CryZ silencing were able to increase and restore the chemosensitivity in both sensitive and resistant A2780 ovarian cancer cells, respectively." (PMID 39021835, 2024). "In this research article we demonstrated that the pharmacological or genetic inhibition of CryZ restores the sensitivity to cisplatin in a model of sensitive or resistant ovarian cancer cells." (PMID 39021835, 2024). "In addition, we revealed that modulation of CryZ activity using ASA or its downregulation by specific siRNA increases sensitivity in both sensitive and drug-resistant human ovarian cancer cells in response to cisplatin treatment." (PMID 39021835, 2024). "Therefore, we demonstrated that CryZ could act as Bcl-2 and Bcl-xl AUBP in A2780 ovarian cancer cells." (PMID 39021835, 2024).
cancer (6 papers, 2010 to 2025). A tumor composed of atypical neoplastic, often pleomorphic cells that invade other tissues. "While CryZ may protect cancer cells from oxidative stress and help them maintain an optimal DNA complement, it can fuel the cancer requirement for energy by activating glutaminolysis." (PMID 35884586, 2022). "Furthermore, increased expression and/or activation of CryZ following acidification of the tumor microenvironment may contribute to cancer cell survival and drug resistance by increasing the anti-apoptotic gene expression in cancer cells." (PMID 35884586, 2022).
tumor (2 papers, 2022). "And the Pearson correlation coefficients between NNMT and CRYZ, and SERPING1 and ANGPTL4 across all TCGA tumor samples were 0.4, 0.43, and 0.62, respectively." (PMID 36386816, 2022).
CRYZ also shares sentences with these, for which no sentence is quoted: acute lymphoblastic leukemia (1 paper); adenoma (1); amyotrophic lateral sclerosis (1); astrocytomas (1); atherosclerosis (1); brain cancer (1); brain tumors (1); cardiovascular disease (1); COVID-19 (1); diabetes (1); ganglioglioma (1); metabolic syndrome (1); neurological disease (1); prediabetes (1); prostate carcinoma (1); Stroke (1); T-cell acute lymphocytic leukemia (1); type 2 diabetes (1).